VCAM1 (vascular cell adhesion molecule 1)
Diseases named in the same sentence as VCAM1 in open-access papers (continued):
Sharing a sentence is not in itself a finding about the gene and the disease.
liver fibrosis (17 papers, 2017 to 2025). "HCV infection also results in upregulation of VCAM1, which are associated with advanced liver fibrosis." (PMID 39605886, 2024). "It was reported that the downregulation of vascular cell adhesion molecule 1 expression associated with LSECs could inhibit the cell adhesion process, thereby alleviating liver fibrosis." (PMID 39741334, 2024). "However, it is still unclear whether VCAM1 is a hallmark of LSEC capillarization and whether VCAM1 can directly modulate HSC activation in liver fibrosis." (PMID 36091042, 2022). "Further experiments confirmed this data, showing that the specific deletion of VCAM1 in liver endothelial cells resulted in a better liver fibrosis profile in in vitro models." (PMID 40977717, 2025). "VCAM1 inhibition attenuated proinflammatory monocyte hepatic infiltration, and thereby alleviated liver fibrosis in diet-induced murine MASH models." (PMID 39605886, 2024). "To answer these questions, we employed two mouse models known to induce significant liver fibrosis together with pharmacological blockade, or endothelial cell-specific knockout of VCAM1." (PMID 36091042, 2022). "The principal findings of the present study provide mechanistic insights regarding the role of the adhesion molecule VCAM1 expressed on LSECs in the development of liver fibrosis." (PMID 36091042, 2022). "The mRNA levels of angiogenesis markers, including Angpt1, CD31, and VCAM-1, were also markedly upregulated in the damaged liver, which was consistent with the progression of liver fibrosis." (PMID 30901579, 2019). "We cannot exclude that HSC VCAM-1 could play a role in a NASH or liver fibrosis model different from the two models used here." (PMID 36902241, 2023). "Furthermore, we demonstrated that inhibition of LSEC VCAM1 can ameliorate not only NASH-related liver fibrosis but also liver fibrosis in a more generalized context by employing CCl4-induced liver fibrosis model." (PMID 36091042, 2022). "Inducible endothelial cell-specific Vcam1 deleted mice (Vcam1Δend) and control mice (Vcam1fl/fl) were fed choline-deficient high-fat diet (CD-HFD) to induce NASH or injected with carbon tetrachloride to induce liver fibrosis." (PMID 36091042, 2022). "We also showed that VCAM1 inhibition (both pharmacological and endothelial cell-specific genetic deletion) attenuated proinflammatory monocyte hepatic infiltration, and thereby alleviated liver fibrosis in diet-induced murine NASH models." (PMID 36091042, 2022). "Moreover, the higher the degree of liver fibrosis in BA, the more significant the difference in VCAM-1 expression levels." (PMID 35626874, 2022). "Although serum VCAM-1 levels correlate with hepatic fibrosis in patients with NAFLD, a finding that may be linked with the upregulation of VCAM-1 in activated HSCs, as identified here, our functional results suggest that VCAM-1 in HSCs does not play a pathophysiological role in fibrosis progression." (PMID 36902241, 2023). "Therefore, VCAM-1 might play a key role in the occurrence and liver fibrosis progression and could be used as a screening biomarker and prognosis predictor in BA patients." (PMID 35626874, 2022). "Interestingly, with development of bridging fibrosis at week 52, changes in pathways related to hepatic fibrosis/hepatic stellate cells activation decreased as compared to 24 weeks and were mainly limited to increase in genes for Col4a1, Mmp12, Mmp13 and Vcam1." (PMID 29222421, 2017). "Selective deletion of VCAM1 in LSECs in a murine model of CCl4-induced liver fibrosis also reduces macrophage accumulation in the liver, suggesting that LSEC VCAM1 is important for immune cell infiltration and liver fibrosis." (PMID 40595432, 2025). "Vascular cell adhesion molecule-1 (VCAM-1) mRNA was also significantly increased, and several works highlight the implication of VCAM-1 in predicting liver fibrosis in MAFLD and progression to MASH." (PMID 39595946, 2024).
liver fibrosis (continued). "Hence, the present study shows a critical role of LSEC VCAM1 in HSC activation and is consistent with previous human studies that indicate that serum levels of soluble VCAM1 can predict liver fibrosis severity in NAFLD patients." (PMID 36091042, 2022). "Classical fibrotic mediators and markers (including Tgfb1, Timp1, and Vcam1), collagen of the ECM (including Col4a1, Col4a2, Col16A1, and Col18a1) and cell surface adhesion and signaling integrin (Itga2, Itga5) were found to be differentially expressed in the enriched hepatic fibrosis pathways." (PMID 39747668, 2025). "Taken together, the findings in the current study suggest that VCAM1 in LSECs is not just a scaffold for leukocyte adhesion, but also a direct modulator of liver fibrosis, further strengthening the potential efficacy of targeting VCAM1 in chronic liver disease patients in clinical settings." (PMID 36091042, 2022). "We also treated human HSCs with recombinant VCAM1; in addition, we employed 2-D and 3-D co-culture systems of LSECs and HSCs to mimic the liver microenvironment and show that endothelial VCAM1 promotes LSEC capillarization and liver fibrosis during liver injury." (PMID 36091042, 2022). "KC have an essential role in liver fibrosis in mouse models of ASH and NASH, propagating hepatic inflammation via tumor necrosis factor (TNF) and leukocyte recruitment via intercellular adhesion molecule-1 (ICAM-1) and vascular cell adhesion molecule-1 (VCAM-1)." (PMID 30972062, 2019). "However, as the model of HCD-induced NASH in mice displays extensive liver fibrosis, the majority of HSCs have likely acquired an activated state; hence, our co-staining of liver sections for VCAM-1 and the pan-HSC marker desmin suggests the presence of VCAM-1 on activated HSCs." (PMID 36902241, 2023). "Moreover, while no function of HSC VCAM-1 in liver fibrosis was found here, we cannot exclude that VCAM-1 in other cells could be a therapeutic target in NASH." (PMID 36902241, 2023). "We have previously reported that the LSEC vascular cell adhesion molecule 1 (VCAM1) plays a key role in liver inflammation in nonalcoholic steatohepatitis (NASH) and we now aim to uncover its role in LSEC capillarization and liver fibrosis." (PMID 36091042, 2022). "VCAM1 is not just a scaffold for leukocyte adhesion during liver injury, but also a modulator of LSEC capillarization and liver fibrosis." (PMID 36091042, 2022).
periodontitis (17 papers, 2013 to 2025). An acute or chronic inflammatory process that affects the tissues that surround and support the teeth. "ICAM-1 and VCAM-1 gene polymorphisms have been observed in the Chinese adult population with periodontitis." (PMID 37371602, 2023). "Our findings suggest direct significant associations between elevated baseline serum ICAM-1/VCAM-1 and an increased risk of periodontitis at the follow-up visit." (PMID 37371602, 2023). "A previous study revealed that ICAM-1 rs5498 and VCAM-1 rs1041163 polymorphisms lead to chronic periodontitis." (PMID 33817202, 2019). "Our findings suggest a positive direction for the association between the direct/indirect effect of hs-CRP, ICAM-1, and VCAM-1 and periodontitis development/progression." (PMID 37371602, 2023). "The finding of a direct effect of VCAM-1 on periodontitis corroborates that of a previous small cross-sectional study of aggressive periodontitis." (PMID 37371602, 2023). "It is thought that periodontitis induces the tubulitis because of the overexpression of VCAM-1 and E-selectin under diabetic conditions and promotes the nephropathy." (PMID 33407253, 2021). "This similarity existed in both CP patients and patients with AMI, and it appears to be a reflection of the host response to periodontitis that is reflected in both N and VCAM-1 levels of patients." (PMID 29641752, 2018). "N and VCAM-1 were much higher in periodontitis patients than in healthy subjects prior to periodontal treatment." (PMID 29641752, 2018). "Considering this, the objective of the present study is to assess whether the interaction of baseline serum levels of TNF-α, hs-CRP, ICAM-1, VCAM-1, and adiponectin leads to periodontitis among overweight/obese individuals." (PMID 37371602, 2023). "Lappin and colleagues also observed a predominant recruitment of plasma cells in the gingival/granulation tissues of periodontitis lesions as compared to gingivitis lesions, and that VCAM-1 was recruited at the deep connective tissue, indicating the role of systemic immune response at that location." (PMID 37371602, 2023). "The objective of this study is to assess whether the interaction of baseline serum levels of TNF-α, hs-CRP, ICAM-1, VCAM-1, and adiponectin leads to periodontitis." (PMID 37371602, 2023). "Periodontitis-induced activation of circulating monocytes, their increased adherence to aortic endothelial cells via nuclear factor-κB (NF-κB) p65, and the elevation of vascular cell adhesion molecule 1 (VCAM1) in the latter are considered to be contributing factors to vascular inflammation." (PMID 40862144, 2025). "The observation that the periodontal bone loss in aging WT mice correlates with significant changes in the expression of Del-1, but not of ICAM-1, VCAM1, or E-selectin, further supports the notion that the age-associated Del-1 deficiency is an important determinant of age-associated periodontitis." (PMID 24416060, 2013). "Increased VCAM-1 and ICAM-1 expression recruits inflammatory cells to promote an inflammatory response and is involved in the progression of chronic inflammation and periodontitis." (PMID 37367059, 2023). "In addition, ICAM‐1 and VCAM‐1 are involved in leukocyte‐endothelial cell adhesion, and increased levels of these molecules have been observed in the GCF of individuals with periodontitis compared with periodontally healthy individuals." (PMID 40344491, 2025). "Thus, elevated serum ICAM-1 and VCAM-1 have a significant direct effect and increased hs-CRP has a significant indirect effect on the predicted level of periodontitis at the 3-year follow-up among overweight/obese Hispanic adults." (PMID 37371602, 2023). "Recent studies showed that VCAM-1 and ICAM-1 are expressed in the connective tissue cells, like gingival fibroblasts and human PDL cells, which may be related to the progression of periodontitis." (PMID 34185172, 2022).
periodontitis (continued). "Since the overexpression of VCAM-1 and E-selectin was observed in glomeruli, tubules, and intertubular capillaries in LPS-STZ, it is thought that periodontitis provokes chronic inflammatory events by the renal monocyte-macrophage lineage infiltration under diabetic conditions." (PMID 33407253, 2021). "The plaques from the mice with periodontitis also showed enhanced staining for adhesion molecules such as intercellular adhesion molecule-1 (ICAM-1) and vascular cell adhesion protein-1 (VCAM-1), suggesting the presence of cells with possible endothelial phenotypes in the plaques." (PMID 31257363, 2019). "However, there are no studies specifically addressing the altered GCF profile concurrent with the onset of AMI (i.e. in the first 24 h) and no data are currently available about GCF N and VCAM-1 levels in AMI patients with chronic periodontitis (CP)." (PMID 29641752, 2018).
nephritis (16 papers, 2007 to 2022). Inflammation of renal tissue. "In an age-adjusted linear regression model, VCAM-1 was significantly associated with active nephritis and inversely associated with smoking." (PMID 24647443, 2014). "Elevated plasma levels of VCAM-1, which also plays a role in perpetuating atherosclerotic plaque formation, are associated with nephritis and increased disease activity in SLE patients." (PMID 20482780, 2010). "Urinary ALCAM, PF4, and VCAM-1 are potential biomarkers for predicting kidney disease activity in cSLE and hold potential as surrogate markers of nephritis flares in these patients." (PMID 35720325, 2022). "Although only five patients had active nephritis, the significant increase in levels was not driven by a single outlier and we observed a genuine trend for higher VCAM-1 levels in all cases with active nephritis." (PMID 24647443, 2014). "Recruited inflammatory cells were observed within the kidneys of the anti-GBM nephritis mice, VCAM-1 expression was elevated and renal failure ultimately developed." (PMID 23460853, 2013). "Along with increased renal expression of Il1b, TNF-α, Vcam1 and E-selectin, increased lymphatic vessel density and enhanced expression of Lyve-1 in the kidney further confirm that elevated level of circulating miR-505 leads to kidney inflammation in vivo." (PMID 35571179, 2022). "Additionally, in a prospective study with class II, IV, and V LN patients classified as active or inactive nephritis at the inclusion time; evaluation of the urinary VCAM-1 showed increased levels in active LN." (PMID 34281193, 2021). "A preclinical study used microbubbles targeted to P-selectin and vascular cell adhesion molecule 1 (VCAM-1) to test whether they could be used to detect kidney inflammation after ischemia reperfusion." (PMID 30631428, 2018). "Kidney inflammation is associated with increased production of pro-inflammatory mediators, and up-regulation of adhesion molecules such as Intercellular adhesion molecule-1 (ICAM-1) and vascular cell adhesion molecule-1 (VCAM-1)." (PMID 24896770, 2014). "Likewise, among active nephritis patients, VCAM-1 and CXCL16 levels as well as the urine protein:creatinine ratio were not different between the patients who received a specific medication and those who did not." (PMID 22788914, 2012). "In addition to VCAM-1 on glomerular endothelial cells, laminin β2 may also serve as an adhesive ligand for inflammatory cells in nephritis." (PMID 33749661, 2021). "Urine levels of VCAM-1 and ALCAM were elevated in patients with active LN compared to healthy controls and with quiescent nephritis." (PMID 34281193, 2021). "UUO kidneys show elevated expression levels of monocyte chemoattractant protein-1 (MCP-1), vascular cell adhesion molecule-1 (VCAM-1), and intercellular adhesion molecule-1 (ICAM-1), which promote monocyte infiltration and kidney inflammation." (PMID 23255047, 2013). "In our model of mercury-induced nephritis, the levels of TNF-α and IL1-β cytokines as well as the expression of VCAM-1 molecule were significantly increased at day 13 of the disease in comparison with the controls." (PMID 17250768, 2007). "Among the nonactive nephritis patients, therefore, VCAM-1, CXCL16 and MCP-1 levels and the urine protein:creatinine ratio were not different between the patients who received a specific medication and those who did not." (PMID 22788914, 2012). "Using high-throughput proteomic technologies, the expression levels of VCAM-1 and nine other urinary biomarkers (b2M, calbindin D, cystatin C, IL-18, KIM-1, MCP-1, nephrin, NGAL, and Vitamin D binding protein (VDBP)) were tested in SLE patients with active or inactive nephritis." (PMID 34281193, 2021). "The median (IQR) VCAM-1 levels were also significantly higher in patients with active nephritis than those with inactive nephritis and those with no history of nephritis (515.5 (307.6, 929) vs 276.7 (199.2, 351.9) vs 272.3 (223.6, 343.5) ng/ml, respectively; p < 0.001)." (PMID 24647443, 2014).
nephritis (continued). "The same aptamer was also studied in a murine model of nephritis, in which it abolished glomerular inflammation and the expression of inflammatory markers IL-1α, IL-1β, IL-6, ICAM-2 (intracellular adhesion molecule 2), and VCAM-1 (vascular cell adhesion molecule 1)." (PMID 20657381, 2010).
Atherosclerotic lesion (15 papers, 2012 to 2025). A lesion associated with atherosclerosis, a multifactorial and multipart progressive disease manifested by the focal development within the arterial wall of lesions, that ranges from the development of a fatty streak, plaque progression, and plaque disruption. "In this regard it has been established that inhibition of MCP-1 reduces macrophage levels in atherosclerotic lesions, and blocking VCAM-1 inhibits monocytes from entering the arterial wall." (PMID 37593179, 2023). "It has been shown that expression of both ICAM-1 and VCAM-1 on intimal and medial SMCs is prominent in fibrous plaques and advanced atherosclerotic lesions and that expression of VCAM-1 correlates with intimal neovessels and mononuclear cell infiltration." (PMID 34604206, 2021). "Previous studies suggested that VCAM-1 has a role in the recruitment of leukocytes in early atherosclerotic lesions via interaction with VLA-4 integrins on monocytes and lymphocytes." (PMID 23886346, 2013). "Recruitment of monocytes from the blood stream is tightly regulated by cell adhesion molecules expressed on the vascular endothelium, and VCAM-1 is essential for the development of early atherosclerotic lesions." (PMID 23554922, 2013). "Adhesion molecules such as intercellular adhesion molecule (ICAM)-1, E-selectin, and vascular cell adhesion molecule (VCAM)-1 make the endothelium surface more adhesive to leukocytes and facilitate their migration into the vessel wall (including atherosclerotic lesions)." (PMID 29041979, 2017). "However, TNF-α and IL-1β promote the expression of intercellular adhesion molecule-1 (ICAM-1) and vascular cell adhesion molecule-1 (VCAM-1) in endothelial cells in atherosclerotic lesions." (PMID 23243449, 2012). "Nrf-2 suppresses the expression of the monocyte MCP-1 and of the vascular cell adhesion molecule 1 (VCAM-1), which diminishes the formation of atherosclerotic lesions in rats and rabbits." (PMID 38498532, 2024). "Also, Nrf2 decreased the expression of MCP-1 and VCAM-1 and consequently reduced monocyte adhesion and transmigration to endothelial cells, which reduced MAPK and p38 expression and alleviated the formation of atherosclerotic lesions in mice and rabbits." (PMID 37440431, 2023).